RN7SL60P (RNA, 7SL, cytoplasmic 60, pseudogene)
Gene: Miscellaneous RNA gene on chromosome 13 (98,671,980 to 98,672,278, forward strand). Ensembl gene ENSG00000243366.
Homologues: Orthologues: chimpanzee Metazoa_SRP (96% identical), macaque Metazoa_SRP (94% identical). Paralogues in human: RN7SL2 (84% identical), RN7SL1 (83% identical), RN7SL220P (83% identical), RN7SL3 (82% identical), RN7SL680P (81% identical), Metazoa_SRP (81% identical), RN7SL627P (81% identical), RN7SL732P (81% identical), Metazoa_SRP (80% identical), RN7SL357P (80% identical), RN7SL18P (80% identical), RN7SL566P (80% identical), and 703 more.